GOLGA8H (golgin A8 family member H)
Synonyms: GOLGA6L11
Tractability: No criterion of Open Targets' tractability assessment is met for any kind of drug.
Gene: Protein-coding gene on chromosome 15 (30,604,028 to 30,617,752, forward strand). Ensembl gene ENSG00000261794.
Gene Ontology:
Biological process: Golgi organization
Cellular component: cis-Golgi network; Golgi cis cisterna; Golgi cisterna membrane; Golgi apparatus
Genetic constraint (gnomAD): Loss-of-function variants: 41 observed, 30.57 expected, observed/expected ratio (o/e) 1.34, 90% interval 1.04 to 1.73. The upper end of that interval is the gene's LOEUF score, 1.73, which puts it in group 6 of 6, group 1 being the genes least tolerant of losing a copy. Missense variants: 314 observed, 250.46 expected, observed/expected ratio (o/e) 1.25, 90% interval 1.14 to 1.38. Synonymous variants: 96 observed, 81.46 expected, observed/expected ratio (o/e) 1.18, 90% interval 1 to 1.4.
Homologues: Orthologues: mouse Golga2 (44% identical), dog GOLGA2 (43% identical), tropical clawed frog golga2 (33% identical), zebrafish golga2 (29% identical), Drosophila melanogaster GM130 (22% identical), Caenorhabditis elegans golg-2 (19% identical), rat Golga2l1 (5% identical). Paralogues in human: GOLGA8J (98% identical), GOLGA8K (97% identical), GOLGA8T (97% identical), GOLGA8M (96% identical), GOLGA8O (91% identical), GOLGA8N (90% identical), GOLGA8Q (90% identical), GOLGA8R (90% identical), GOLGA8S (85% identical), GOLGA8F (81% identical), GOLGA8G (81% identical), GOLGA8A (66% identical), and 6 more.